ATXN7L3B (ataxin 7 like 3B)
Description:
By binding to ENY2, interferes with the nuclear functions of the deubiquitinase (DUB) module of the SAGA complex which consists of ENY2, ATXN7, ATXN7L3 and the histone deubiquitinating component USP22. Affects USP22 DUB activity toward histones indirectly by changing the subcellular distribution of ENY2 and altering ENY2 availability for ATXN7L3 interaction. Regulates H2B monoubiquitination (H2Bub1) levels through cytoplasmic sequestration of ENY2 resulting in loss of nuclear ENY2-ATXN7L3 association which destabilizes ATXN7L3. Affects protein expression levels of ENY2 and ATXN7L3.
Synonyms: lnc-SCA7
Tractability: PROTAC: ubiquitination databases record sites on it; its protein half-life has been measured.
Gene: Protein-coding gene on chromosome 12 (74,537,835 to 74,545,430, forward strand). Ensembl gene ENSG00000253719.
Subcellular location: Cytoplasm
Subcellular location (Human Protein Atlas): Nucleoplasm
Gene Ontology:
Molecular function: protein binding
Biological process: regulation of gene expression
Cellular component: cytoplasm
Genetic constraint (gnomAD): Loss-of-function variants: 4 observed, 5.12 expected, observed/expected ratio (o/e) 0.78, 90% interval 0.38 to 1.66. That is too few expected variants to judge how well the gene tolerates losing a copy. Missense variants: 120 observed, 112.11 expected, observed/expected ratio (o/e) 1.07, 90% interval 0.92 to 1.25. Synonymous variants: 63 observed, 45.78 expected, observed/expected ratio (o/e) 1.38, 90% interval 1.12 to 1.7.
Homologues: Orthologues: guinea pig ATXN7L3B (100% identical), macaque ATXN7L3B (100% identical), chimpanzee ATXN7L3B (99% identical), pig ATXN7L3B (99% identical), rat Atxn7l3b (96% identical), mouse Atxn7l3b (94% identical), dog ATXN7L3B (79% identical), Drosophila melanogaster Sgf11 (19% identical). Paralogues in human: ATXN7L3 (53% identical), ATXN7L2 (16% identical), ATXN7 (11% identical), ATXN7L1 (11% identical).
Diseases named in the same sentence as ATXN7L3B in open-access papers:
ATXN7L3B is named in the same sentence as 4 diseases in open-access papers, as found by Europe PMC text mining. Sharing a sentence is not in itself a finding about the gene and the disease. The quoted sentences say what the papers report.
Ataxia (1 paper, 2023). Ataxia refers to impaired coordination of voluntary muscle movement. "Ataxin-7-like protein 3B (ATXN7L3B), a downstream target of miR-15a-5p, showed an involvement in human neurodevelopmental delay and ataxia, which possibly have a more dramatic effect on brain development in children who had been infected with SARS-CoV-2." (PMID 38057315, 2023).
Hypertension (1 paper, 2023). The presence of chronic increased pressure in the systemic arterial system. "Up until now, the association of other genes, such as ATXN7L3B, LOC646588, EYS, MGEA5, and SAE1, with hypertension had not been extensively researched, but they may also serve as candidates to be further verified." (PMID 36869404, 2023).
cancer (1 paper, 2022). A tumor composed of atypical neoplastic, often pleomorphic cells that invade other tissues. "Therefore, AC006116 and AC073046, as its ceRNAs, could regulate the expression of ATXN7L3B and were also closely related to cancer." (PMID 35721492, 2022).
ATXN7L3B also shares sentences with these, for which no sentence is quoted: Neurodevelopmental delay (1 paper).